MYLK (myosin light chain kinase)
Diseases named in the same sentence as MYLK in open-access papers (continued):
Sharing a sentence is not in itself a finding about the gene and the disease.
prostate carcinoma (12 papers, 2008 to 2024). A carcinoma that arises from epithelial cells of the prostate gland. "The MYLK gene significantly influenced the progression of prostate cancer, which is a sex hormone-dependent disease in males, and the MYLK variants found in this study were associated with benign breast tumors related to female hormones, in line with the previous study." (PMID 33800915, 2021). "MYLK1 gene encodes MYLK, a Ca2+/CaM-dependent enzyme that has been identified as a promoter of prostate cancer progression." (PMID 38441550, 2024). "Through the application of bioinformatics technology, we identified the potential key genes associated with the occurrence and development of prostate cancer as FGF2, FLNA, VCL, FLNC, CAV1, ACTC1, and MYLK." (PMID 32547947, 2020). "MYLK is down-regulated by androgens in human prostate cancer cells, and acts as a central mediator of migration, proliferation and invasion of prostatic adenocarcinoma cell line." (PMID 27626693, 2016). "The best three single gene discriminators are MYLK, PALLD and CAV1 for prostate cancer, having 73.4%, 71.9% and 71.1% classification accuracy on the training set and 83.5% and 62.3%, 69.6% and 72.6%, and 94.2% and 75.5% on the two test sets, respectively." (PMID 21060876, 2010). "Five of these top seven genes namely, MYLK, KLK2, KLK3, LTF and TGM4 had already been specifically related to prostate carcinoma." (PMID 19055846, 2008). "The MYLK, KLK2, KLK3, HAN11, LTF, CSRP1 and TGM4 genes presented significant changes in their functional connectivity between normal and tumoral conditions and were also classified as the top seven most informative genes for the prostate cancer genesis process by our discriminant analysis." (PMID 19055846, 2008).
Sepsis (11 papers, 2008 to 2024). Sepsis is defined as life-threatening organ dysfunction caused by a dysregulated host response to infection. "We have reported previously that MYLK genetic variants conferred risk for severe sepsis and sepsis-associated acute lung injury." (PMID 26063982, 2015). "A few race-specific single nucleotide polymorphism variants of MYLK are linked to asthma, acute lung injury and sepsis." (PMID 25072053, 2014). "A case–control study found that myosin light chain kinase (MYLK) genetic variants were associated with increased risk of sepsis-associated ALI." (PMID 24209603, 2013). "Genetics-based studies have revealed the association of polymorphisms in the myosin light chain kinase (MYLK) gene with increased risk of sepsis and acute pulmonary injury." (PMID 20707930, 2010). "MYLK encodes protein isoforms involved in multiple components of the inflammatory response, including apoptosis, vascular permeability, and leukocyte diapedesis, and is a well-established candidate gene in sepsis- or trauma-induced ARDS." (PMID 38558813, 2024). "However, miR-15a can potentially promote NF-ΚB signaling by negatively regulating IKK-α and inhibit genes encoding vascular endothelial growth factor (VEGF)A, VEGFC, and myosin light chain kinase, increasing vascular permeability in sepsis." (PMID 35305556, 2022). "First, both miR-15a and miR-27a are known to or are predicted to target and inhibit genes that increase vascular permeability in the setting of sepsis including VEGFA, VEGFC and MYLK." (PMID 26683209, 2015).
Aortic dissection (9 papers, 2014 to 2025). Aortic dissection refers to a tear in the intimal layer of the aorta causing a separation between the intima and the medial layers of the aorta. "In the largest reported case series, pathogenic MYLK variants have been reported to cause aortic dissection in aortas with minimal prior dilatation (mean SoV 39 ± 8 mm; ascending aorta 43 ± 4.9 mm)." (PMID 39713234, 2024). "Individuals carrying this deletion in MYLK have a high risk of presenting with an acute aortic dissection or rupture." (PMID 27586135, 2016). "Genetic and functional studies show that heterozygous loss-of-function mutations in MYLK are associated with aortic dissection." (PMID 24962627, 2014). "Preventing aortic dissection in MYLK mutation carriers remains a clinical challenge." (PMID 27586135, 2016). "In this study, we report a young nonsyndromic male with aortic dissection carrying two missense variants of unknown significance in MYLK and FBN1, whose segregation analysis helped evaluate their pathogenicity and was useful for genetic counseling in the proband and his families." (PMID 39185084, 2024). "It is interesting to note that MYLK pathogenic variants can cause aortic dissection with little to no enlargement of the aorta." (PMID 39185084, 2024). "We found an 18 Mb homozygous region on chromosome 3 (3q21.1), which harbors MYLK, a gene known to predispose to aortic dissection without aneurysm." (PMID 29544503, 2018). "The absence of MYLK is known to be associated with several diseases, including aortic dissections." (PMID 33389819, 2021). "The remaining 30 (17%) women were categorized in the ‘other’ group, which included women who harboured a rare PV in PKRG1 (n = 1), LOX (n = 1), or MYLK/FLNA (n = 1), or who had pre-existing aortic pathologies such as thoracic aortic dilatation (n = 23) or aortic dissection (n = 4)." (PMID 40576452, 2025). "Inhibition of myosin light chain kinase by ML-7 or indirectly by a calcium channel blocker, nifedipine, or a Rho kinase inhibitor, fasudil, did not significantly alter the incidence of NE-triggered aortic dissection, although with a confounding lowering of blood pressure by the former 2 agents." (PMID 39932797, 2025).
thoracic aortic aneurysm (9 papers, 2017 to 2025). An aneurysm formed in the wall of the proximal portion of the descending aorta proceeding from the arch of the aorta. "Herein, we inform on the clinical, genetic and pathological characteristics of nine living and deceased members of a large consanguineous Arab family with thoracic aortic aneurysm and dissection who carry a missense mutation c.4471G > T (Ala1491Ser), in exon 27 of MYLK gene." (PMID 29544503, 2018). "Causal mutation of MYLK was identified in thoracic aortic aneurysm patients." (PMID 27965470, 2017). "The age at dissection varied according to the underlying NS‐TAD form, with a mean age of presentation of 32 years for the familial thoracic aortic aneurysm and dissection forms associated with the mutations of the PRKG1 gene and of 54 years for those associated with the mutation of the MYLK gene." (PMID 30371227, 2018).
atherosclerosis (8 papers, 2015 to 2023). A disease characterized by the build-up of fatty material and calcium deposition in the arterial wall resulting in partial or complete occlusion of the arterial lumen. "Notably, a genetic deficiency or inhibition of myosin light-chain kinase in mice attenuates endothelial permeability, leukocyte transendothelial migration, and atherosclerosis." (PMID 32751580, 2020). "The related genes such as TOMM5, and MYLK have been reported to have implications in diabetes, and PDLIM1 and CAMK2G were found to be related to atherosclerosis." (PMID 35508613, 2022). "Melatonin also plays an important role in the development of atherosclerosis through the regulation of the MAPK pathway and suppression of the activity of myosin light-chain kinase (MLCK), therefore decreasing endothelial dysfunction and the formation of atheromatous plaques." (PMID 35453312, 2022). "Therefore, we speculate that MYLK and SMTN reduce CD56 + NK cell involvement in the occurrence and progression of atherosclerosis." (PMID 37963970, 2023).
hepatocellular carcinoma (8 papers, 2018 to 2025). A malignant tumor that arises from hepatocytes. "It has been demonstrated that MYLK influences the progression of hepatocellular carcinomas by catalysing the phosphorylation of myosin light chain (MLC)." (PMID 40463716, 2025). "MYLK promotes the progression of hepatocellular carcinoma by altering the cytoskeleton to enhance epithelial-mesenchymal transition (EMT)." (PMID 32547947, 2020). "When myosin light chain kinase (myosin light chain kinase, MLCK) was inhibited in hepatocellular carcinoma cells, both p38 MAPK phosphorylation and E-calmodulin expression were elevated, and cell migration was significantly inhibited." (PMID 39852131, 2024).
aortic aneurysm (7 papers, 2018 to 2025). A ruptured aneurysm located in the wall of the proximal portion of the descending aorta proceeding from the arch of the aorta. "MYLK is targeted by mutations in genetic forms of aortic aneurysms." (PMID 40081573, 2025). "Clinically, this mutation presented as an aortic aneurysm and dissection of the thoracic and/or abdominal aorta and the subclavian, innominate, renal, superior mesenteric and iliac arteries in two distinct phenotypes that are correlated with homozygosity or heterozygosity for the MYLK variant." (PMID 29544503, 2018). "Patient I35 had two pathogenic nonsense variants on MYLK (OMIM: *600922) and MYF5 (OMIM: *159990), associated with aortic aneurysm and familial thoracic (OMIM: 613780), and external ophthalmoplegia with rib and vertebral anomalies (OMIM: 618155), respectively." (PMID 36361644, 2022).
heart failure (7 papers, 2015 to 2025). Inability of the heart to pump blood at an adequate rate to meet tissue metabolic requirements. "The SPEG gene encodes a myosin light chain kinase and regulator of cardiac calcium homeostasis with mutations causing dilated cardiomyopathy, atrial fibrillation, and heart failure." (PMID 39774334, 2025). "Down regulation of MYLK expression increases the risk of heart failure." (PMID 27884156, 2016). "Heart failure is a complex molecular disease process involving more than IL-6 and MYLK." (PMID 27884156, 2016).
non-small cell lung carcinoma (7 papers, 2012 to 2025). A group of at least three distinct histological types of lung cancer, including non-small cell squamous cell carcinoma, adenocarcinoma, and large cell carcinoma. "In similar articles, the expression of MYLK in non-small cell lung cancer tissues was significantly lower than that in adjacent tissues and normal tissues by bioinformatics analysis." (PMID 32547947, 2020). "However, the expression of MYLK in non-small cell lung cancer tissues was significantly lower than those in paracancerous and normal tissues, findings that are consistent with our studies." (PMID 39762799, 2025). "On the other hand, MYLK expression at both mRNA and protein levels was significantly reduced in non-small-cell lung cancer compared to healthy lung tissue, which may result in increased mutagenesis that promotes cell proliferation and drives carcinogenesis." (PMID 31795319, 2019). "Also, low levels of MYLK were found in non-small cell lung cancer." (PMID 32817744, 2020). "A significant positive correlation was also found between the expression levels of myosin light chain kinase (which activates NMIIA) and the likelihood of disease recurrence and metastasis for patients with non-small-cell lung carcinoma." (PMID 23203126, 2012).
aneurysm (6 papers, 2018 to 2025). Bulging or ballooning in an area of an artery secondary to arterial wall weakening. "The knock down of myosin light chain kinase in human brain SMCs caused effects similar to those observed in aneurysm SMCs." (PMID 30555299, 2018). "There are common pathways and mechanisms, some including MYLK, in aneurysm formation and BS pathogenesis." (PMID 36834577, 2023). "We found that 180 proteins were differentially expressed between the aneurysm and control samples, among which 88 were increased and 92 (including myosin light chain kinase) were decreased in aneurysms compared to control tissues." (PMID 30555299, 2018). "The expression and function of myosin light chain kinase in aneurysms were examined." (PMID 30555299, 2018). "The protein expression levels of COL4A2, MYLK, and VCL were decreased after SMCs were intervened with TNF‐α, consistent with the results from mass spectrometry on aneurysm samples (E‐G)." (PMID 33389819, 2021). "We found several proteins whose expression levels were significantly different, such as MYLK, VCL, and collagen type IV, in both rabbit and human aneurysms, suggesting that these proteins may be vital in the development of aneurysms." (PMID 33389819, 2021). "We found that COL4A2, MYLK, VCL, and TAGLN may be related to aneurysm development." (PMID 33389819, 2021).
colitis (6 papers, 2009 to 2024). Inflammation of the colon. "A constitutively active myosin light chain kinase (MLCK) in intestinal epithelia transgenic mice results in a colitis-prone phenotype, with an increased number of intraepithelial bacteria in the colonocytes of these mice." (PMID 38012609, 2023). "The importance of barrier maintenance in IBD is further highlighted by the development of colitis in mice expressing constitutively active myosin light chain kinase, which is involved in regulating the epithelial barrier." (PMID 19709415, 2009). "One of the causes is thought to be the disruption of intestinal tight junctions by the PPI-induced increase in extracellular pH levels, triggering the activation of myosin light chain kinase via p38 pathways, as shown in DSS-induced colitis mouse models." (PMID 39249550, 2024). "MMPs, especially highly elevated MMP-9 in patients with IBD, increase in intestinal epithelial tight permeability through the P38 kinase signaling pathway-mediated myosin light chain kinase (MLCK) gene and was responsible for the inflammatory response and tissue damage in mouse models of colitis." (PMID 33015178, 2020).
colon carcinoma (5 papers, 2018 to 2025). "MYLK downregulation is a hallmark of colon cancer metastasis, and MYLK mRNA and smooth muscle MLCK (smMLCK) protein are dysregulated in lung cancer." (PMID 30161129, 2018). "MYLK is associated with signaling pathways that include Rho/ROCK and Ca2+ signaling, which participate in colon cancer metastasis." (PMID 30161129, 2018). "PTPRA regulates cellular contractility through SFKs and myosin light-chain kinase (MLCK) and its presence is required for colon cancer cell invasiveness." (PMID 33710332, 2021). "The pseudogene MYLKP1, derived from MYLK which encodes myosin light chain kinase (MLCK), exhibits high expression in lung and colon cancer cell lines and tissues but is absent in normal lung or colon tissue." (PMID 40556338, 2025). "We previously reported that MYLKP1, the pseudogene of MYLK that encodes myosin light chain kinase (MLCK), is highly expressed in lung and colon cancer cell lines and tissues but not in normal lung or colon." (PMID 30161129, 2018).
dilated cardiomyopathy (5 papers, 2022 to 2025). Cardiomyopathy which is characterized by dilation and contractile dysfunction of the left and right ventricles. "Striated preferentially expressed protein kinase (SPEG), a myosin light chain kinase, is mutated in centronuclear myopathy (CNM) and/or dilated cardiomyopathy." (PMID 35763354, 2022). "The myosin light chain kinase (MLCK) family of proteins is known to be important in phosphorylating sarcomeric proteins and gene mutations in this family leads to the development of dilated cardiomyopathy in humans and mice." (PMID 38145999, 2024). "Notably, among these proteins, MYL2, ACTN1, MYLK, COL1A2, COL6A2, and COL6A3 have been associated with dilated cardiomyopathy and hypertrophic cardiomyopathy pathogenic processes in previous studies." (PMID 37649075, 2023).
inflammatory bowel disease (5 papers, 2020 to 2025). A spectrum of small and large bowel inflammatory diseases of unknown etiology. "MYLK upregulated expression was reported to correlate with the severity of inflammatory bowel disease, a major risk for the development of gastrointestinal malignancies." (PMID 33255928, 2020). "In particular, TNF-α plays a critical role in inflammatory bowel disease, where it can synergize with IFN-γ to regulate multiple tight-junction (TJ) proteins, including myosin light chain kinase, occludin, and ZO-1, as well as claudin-1 and claudin-2 (106, –, 109), which are also regulated by IL-17." (PMID 32958528, 2020).
lung cancer (5 papers, 2012 to 2024). A malignant neoplasm involving the lung. "in their study showed that the low expression of both the MYL9 and MYLK were associated with non‐small cell lung cancer (NSCLC)." (PMID 38872418, 2024). "A study of MYL9 in nonsmall cell lung cancer (NSCLC) showed that the expression levels of and MYL9 were significantly lower in cancer tissue than those in the paraneoplastic and normal tissues, suggesting that low MYLK and MYL9 expressions might be associated with the development of NSCLC." (PMID 34729929, 2022). "In addition, knockdown of FLJ20420 expression also significantly increased the expression of PRKCBP2, TGFBR1, TGFB2, CLCN4, TRAF3, MYLK and ACTA2, while decreasing the expression of SMAD5 and prot-LBC, resulting in an increased apoptotic potential in FLJ20420-silenced lung cancer cells." (PMID 22567091, 2012).
Marfan syndrome (5 papers, 2014 to 2025). A disorder of the connective tissue. "Mutations in MYLK cause a vascular disease that is different both from that in Marfan syndrome and from that associated with mutations that disrupt TGF-β signaling pathways (mutations in TGFβR1, TGFβR2, SMAD3, TGFβ2, TGFβ3)." (PMID 27586135, 2016). "Among them, 51 patients had genetically confirmed HTAD (Marfan syndrome (FBN1), Loeys-Dietz syndrome (TGFBR1, TGFBR2, SMAD3, TGFB2), vascular Ehlers-Danlos syndrome (COLSA1), and non-syndromic HTAD (ACTA2, MYH11, MYLK))." (PMID 41310758, 2025).
cardiac hypertrophy (4 papers, 2016 to 2025). "Leading kinases included AKT1, MAPK1, MYLK, INSR, and ABL1, all of which are implicated in stress response and cardiac hypertrophy, particularly under physiological conditions." (PMID 40725470, 2025). "Specifically, markers of non-cardiac differentiation, such as those for vascular endothelium (VWF) and non-cardiac muscle (CDH6, CNN2 and MYLK) were downregulated, while genes encoding for cardiac hypertrophy (IGF1R) and calcium handling (CAMK2B) were upregulated." (PMID 26785135, 2016). "Evidence from studies conducted in a knockout myosin light chain kinase (MLCK) mouse model and a cardiac-specific overexpressing MLCK transgenic mouse model suggests an important role for cardiac myosin light chain (MLC) phosphorylation in the evolution of cardiac hypertrophy to HF." (PMID 35456920, 2022).
colorectal cancer (4 papers, 2017 to 2025). A primary or metastatic malignant neoplasm that affects the colon or rectum. "First, we preliminarily explored the expression characteristics of MAMDC2 in colorectal cancer and its potential association with the EMT process and MYLK expression in CAFs through bioinformatics analysis and in vitro experiments." (PMID 40427044, 2025). "Statistical analysis of MYLK gene expression differences in colorectal cancer patients and normal population and prognosis results from The Cancer Genome Atlas(TCGA) data." (PMID 38735014, 2024). "ATRA also can inhibit RKO colorectal cancer cell migration by downregulating myosin light-chain kinase expression via the extracellular signal-regulated kinase-1/Mitogen-activated protein kinase signalling pathway." (PMID 29184163, 2017).
acute respiratory distress syndrome (3 papers, 2015 to 2023). Progressive and life-threatening pulmonary distress in the absence of an underlying pulmonary condition, usually following major trauma or surgery. "MYLK is especially interesting as dysregulation of MYLK has been linked to acute respiratory distress syndrome—one of the symptoms of severe COVID-19 disease." (PMID 34548480, 2021).